FFAR2 (free fatty acid receptor 2)
Diseases named in the same sentence as FFAR2 in open-access papers (continued):
Sharing a sentence is not in itself a finding about the gene and the disease.
Obesity (continued). "For example, the majority of studies show that activation of FFAR2/3 signaling ameliorates obesity/T2D pathology, however, some studies show the opposite." (PMID 32521775, 2020). "In contrast, FFAR2 KO mice fed with HFD show lower body fat mass, improved glucose control, lower plasma lipids, increased body temperature with BAT density, and lower WAT inflammation—indicating that FFAR2 deletion protects HFD-induced obesity/T2D." (PMID 32521775, 2020). "The fact that GPR43-deficient (Ffar2-KO) mice are completely protected from high-fat diet-induced obesity, dyslipidemia, and fatty liver supports the importance of SCFAs/GPR43 signaling in the development of NAFLD." (PMID 31726747, 2019). "A recent report showed Ffar2 knockout mice on HFD are protected from diet-induced obesity, most likely due to increases in energy expenditure and fecal energy output." (PMID 22506074, 2012). "Similarly, dietary fiber intake can increase the production of SCFAs by gut microbiota, which subsequently stimulates GLP-1 secretion by acting on GPR41/FFAR3 and GPR43/FFAR2 on gut endocrine L cells, thereby improving obesity and IR." (PMID 41321496, 2025). "FFAR2 (GPR43) selectively binds to acetate, while propionate and butyrate show high affinity for FFAR3, thereby activating metabolic pathways associated with obesity and related diseases." (PMID 39769394, 2024). "The majority of findings to date indicate that activation of FFAR2/3 by SCFAs could be a promising anti-obesity strategy, with direct implications for adipose tissue function." (PMID 36678142, 2023). "Propionate and butyrate could prevent HFD-induced obesity by modulating free fatty acid receptors 2 and 3 (FFAR2 and FFAR 3) and gut microbes." (PMID 37430929, 2022). "In addition to serving as an energy substrate, butyrate functions as a signal molecule in reducing energy intake and obesity via activating FFAR2/3 and promoting the secretion of glocagen-like peptide-1 (GLP-1)." (PMID 34572499, 2021). "Therefore, further studies are critically needed to develop better understanding about the role of FFAR2/3 in regulating metabolic functions, and pathology of obesity/T2D." (PMID 32521775, 2020). "Additionally, FFAR2 KO mice on normal chow (NC) shows reduced β-cell mass and develop obesity and T2D characterized with increased glucose intolerance and FFA levels." (PMID 32521775, 2020). "Since the inflammatory response is also related to the development of obesity and type 2 diabetes, the regulation of immune function via FFAR2 may be also related to the metabolic beneficial effects by SCFAs." (PMID 25875123, 2015). "However, expanding to test the whole pathway using a multi-set approach does detect significant associations at the pathway level, allowing us to examine more closely the individual gene tests, identifying potentially novel associations between FFAR2 and ELOVL2 with obesity." (PMID 33240333, 2020). "As signaling molecules, SCFAs exert anti-obesity effects by activating PPAR-γ in the liver and WAT and G protein-coupled receptors GPR43/FFAR2 and GPR41/FFAR3." (PMID 40867585, 2025). "Recent studies have shown that SCFAs, specifically propionic acid and butyric acid, activate FFAR2/FFAR3 receptors in intestinal L-cells, stimulating PYY secretion and helping prevent and alleviate obesity." (PMID 40867585, 2025). "Among the different FFARs that have been identified, there is particular interest in the physiological roles of FFAR2/GPR43 and its potential use as a novel therapeutic target in health disorders, such as obesity and insulin resistance." (PMID 40909171, 2025). "Furthermore, butyrate generated by butyrate-producing bacteria, such as Feacalibacterium prausnitzii, may also exert anti-obesity effects by stimulating GLP-1 secretion from colon L cells via fatty acid receptor (FFAR2)-mediated signaling and mitigating insulin resistance." (PMID 39545049, 2024).
Obesity (continued). "FFAR2 (GPR43) and FFAR3 (GPR41) are selectively activated by SCFAs, thus activating metabolic pathways in the setting of obesity and obesity-related diseases." (PMID 36678142, 2023). "Interestingly, FFAR2 deficiency did not exacerbate the obesity phenotype of the mice." (PMID 34530928, 2021). "Activation of free fatty acid receptor 2 (FFAR2) on enteroendocrine L-cells mediates secretion of glucagon-like peptide 1 (GLP-1) and peptide YY (PYY), key regulators of central appetite control with therapeutic relevance to obesity." (PMID 41844830, 2026). "Animal experiments found that inulin could stimulate the production of SCFAs in wild-type or FFAR2-/- mice, drive an increase in the number of cells that secrete PYY, increase the release of PYY, and then suppress appetite to control obesity." (PMID 40697558, 2025). "Moreover, when FFAR2 KO mice fed with high fat diet (HFD) show higher energy expenditure, plasma FFA level and higher food intake leads to obesity as compared to WT mice." (PMID 32521775, 2020). "However, growing understanding using evolved computational in-silico analyses and their significant role in several human diseases such as obesity, diabetes, IBD, and aging, FFAR2/3 are emerging as potential therapeutic targets." (PMID 32521775, 2020). "Interestingly, FFAR2 knockout mice were protected from HFD-induced obesity and metabolic abnormalities suggesting a negative influence of FFAR2 on metabolic homeostasis." (PMID 35203397, 2022). "FFAR2 deficiency exacerbated NAFLD/NASH without affecting the obese phenotype or peripheral glucose tolerance, which is not consistent with the results of a previous study, demonstrating that FFAR2 deficiency exacerbates obesity and glucose intolerance." (PMID 34530928, 2021). "For example, HFD feeding to FFAR2 KO mice shows improved oral glucose tolerance test (OGTT) and insulin sensitivity along with lower fat mass and increased lean mass compared to wild type (WT) mice, indicating that the deletion of FFAR2 protects HFD-induced obesity/T2D." (PMID 32521775, 2020). "However, inulin (a prebiotics that promotes SCFA production) feeding increases L-cell population in HFD-fed mice and protects against obesity/T2D, while such effects of inulin disappeared in FFAR2 KO mice, suggesting that FFAR2 is required for acetate action to prevent HFD-induced obesity/T2D." (PMID 32521775, 2020). "Taken together, these findings suggest that the acetate–FFAR2 molecular circuit protects against the development of NAFLD/NASH by directly regulating hepatic metabolism, rather than by ameliorating obesity." (PMID 34530928, 2021).
asthma (44 papers, 2012 to 2026). "FFAR2 and FFAR3 are both associated with metabolic diseases and have become effective targets for the treatment of type 2 diabetes, asthma, cardiovascular diseases, and metabolic syndrome." (PMID 40332278, 2025). "Both FFAR2 and FFAR3 are associated with metabolic diseases, and they have become effective targets for the treatment of type 2 diabetes, asthma, cardiovascular disease, as well as metabolic syndrome." (PMID 32887215, 2020). "Interestingly, the lack of FFAR2 led to unresolved inflammation in several animal models of inflammation, including allergen-induced airway inflammation, suggesting FFAR2 activation by short-chain fatty acids would be beneficial to reduce asthma." (PMID 23844029, 2013).
Insulin resistance (38 papers, 2014 to 2025). Increased resistance towards insulin, that is, diminished effectiveness of insulin in reducing blood glucose levels. "In support of this view, liver-specific FFAR2 deficiency recapitulated the exacerbation of insulin resistance present in Ffar2−/− mice." (PMID 34530928, 2021). "During pregnancy, the measurable changes in circulating SCFA composition, increased FFAR2 expression, enhanced FFAR2 signaling, increased insulin secretion, and β cell proliferation compensate for pregnancy-related insulin resistance in together." (PMID 38248846, 2024). "The deletion of liver-specific FFAR2 worsens insulin resistance, causing inflammation, hypercholesterolemia and liver fibrosis, suggesting a protective effect of GPCR activity mediated by acetate and FFAR2." (PMID 35327352, 2022). "We also illustrated that FFAR2 deficiency exacerbated NAFLD/NASH progression and worsened insulin resistance in the liver." (PMID 34530928, 2021). "This liver-specific silencing of Ffar2 exacerbated hepatic insulin resistance and lipid accumulation in HFC diet-fed mice." (PMID 34530928, 2021). "To examine the influence of FFA2 in regulating adaptive β cell mass expansion in response to insulin resistance, we also assessed β cell mass in WT and Ffar2−/− mice at 26 weeks, following 20 weeks of high fat diet (HFD)." (PMID 27324831, 2016). "Previously, we observed that female Ffar2-/- mice exhibit impaired glucose tolerance during pregnancy, at a time of heightened insulin resistance, as compared to control mice." (PMID 27959892, 2016). "Here, we hypothesized that increased FFAR2 expression and reduced FFAR4 and SCD1 expression in SAT of patients with type 2 diabetes mellitus in the fasted state associate positively with insulin resistance and inversely with beta cell function." (PMID 30190473, 2018). "We hypothesized that increased FFAR2 expression and reductions in FFAR4 and SCD1 expression in SAT of type 2 diabetes mellitus patients associate positively with insulin resistance and impaired beta cell function." (PMID 30190473, 2018). "Thus, FFAR2 may serve as a potential target for diabetes prevention strategies via inhibition of lipid-induced insulin resistance." (PMID 30190473, 2018). "The elevation of FFAR2, FFAR3, GLP-1, and PYY by DOP treatment was another mechanism of insulin resistance improvement in prediabetic mice." (PMID 37372523, 2023). "Interestingly, transgenic mouse model with FFAR2 overexpression in adipocytes was resistant to HFD-induced body weight gain and exhibited attenuated insulin resistance." (PMID 37484954, 2023). "In addition, the upregulation of FFAR2, FFAR3, GLP-1, and PYY was reported to improve insulin resistance." (PMID 37372523, 2023). "Taken together, we hypothesized that the expression of FFAR2 and FFAR3 was significantly increased in high-fat diet-fed mice in a compensatory manner to improve insulin resistance in visceral fat." (PMID 34074061, 2021).
colon cancer (29 papers, 2012 to 2024). "Ffar2 regulates metabolite sensing by colonic innate lymphoid cells, and its loss exacerbates colonic inflammation and promotes colon cancer." (PMID 39683640, 2024). "DKK3 is an inflammatory suppressor and its mRNA level decreased after dextran sodium sulfate (DSS) induction in the free fatty acid receptor 2 (FFAR2)-deficient colon tumor mice." (PMID 36282328, 2022). "Loss of FFAR2 has been shown to promote colon cancer and leukemia in murine models, and expression levels are relatively diminished among TCGA melanoma tissues vs. several other cancers according to the Human Protein Atlas." (PMID 33108391, 2020). "Since Ffar2 was downregulated in colon cancers, an inflammation-associated colon carcinogenesis model was used to test the role of Ffar2 in colonic inflammation and carcinogenesis." (PMID 27348268, 2016). "Strong evidence suggest that FFAR2 acts a colon tumor suppressor and its deficiency has been associated with an enhanced downstream cAMP–PKA–CREB pathway, which resulted in epigenetically decreased levels of inflammation suppressors or the activation of the Wnt pathway." (PMID 33113952, 2020). "Interestingly, in colon cancer FFAR2 acts as an epigenetic tumor suppressor since loss of FFAR2 leads to high-level of H3K4me3 promoting colon carcinogenesis." (PMID 32517300, 2020). "Interestingly, Li-Shu’s lab showed that loss of free fatty acid receptor 2 dampens BRBs’ anti-colon cancer ability in mice." (PMID 34308365, 2020). "The literature claims that FFAR2 immunoreactivities are evident in nearly all normal colon tissue samples, and successively reduced, or even lost in colon cancer tissues in a grade-dependent manner." (PMID 39432182, 2024). "Then, they observed that an FFAR2 agonist reduced the number of colon tumors, and decreased the frequency of IL27 + DCs in tumors of ApcMin/+/DSS mice." (PMID 39432182, 2024). "The most recent findings revealed that FFAR2 is an important mediator for HDAC inhibition induced by butyrate, indicating an epigenetic tumor suppressor role for FFAR2 and blocking colon cancer progression." (PMID 33897470, 2021). "It is important to note that, in a similar manner to that reported with FFAR2, the reduced expression of HCAR2 associated to colon cancer, difficult the potential beneficial effects of the activation of this receptor on tumor progression." (PMID 33113952, 2020). "Short-chain fatty acids then activate free fatty acid receptor 2 on the cell membrane and function as histone deacetylase inhibitor in colon epithelium and immune cells such as neutrophils in mice bearing colon tumors." (PMID 34308365, 2020). "Further studies reinforced this last observation in human colon cancer, and demonstrated a protective role for FFAR2 in a variety of mouse models of colon carcinogenesis." (PMID 33113952, 2020). "The expression of FFAR2 is frequently reduced or abolished in colon cancer cells; in fact restoration in the FFAR2 expression followed by propionate treatment induced G0/G1 cell cycle arrest and activated caspases, leading to apoptotic cell death." (PMID 30903435, 2019). "Further experimental studies confirmed that intestinal barrier function-related proteins, inflammatory and immune-related signaling pathways (STAT3 and Nod pathways), and free fatty acid receptor 2 (FFAR2) inhibited the “inflammatory transformation” of colon cancer." (PMID 36844438, 2023). "FFAR2(GPR43) is downregulated in human colon cancers that matched the adjacent healthy tissue." (PMID 34869511, 2021). "Therefore, it is suggested that there is a possible link between the gut microbial fermentation products and FFAR2 in lowering colon cancer incidence." (PMID 30903435, 2019). "Here, we show FFAR2 is down modulated in human colon cancers than matched adjacent healthy tissue." (PMID 27348268, 2016). "We will also summarize the current knowledge of the implications of FFAR2 and HCAR2 on gut inflammation and colon cancer." (PMID 33897470, 2021).
colon cancer (continued). "The functional role of this receptor was demonstrated in human colon cancer cell lines in which FFAR2 mRNA expression was almost absent and the restoration of this receptor, and its activation by SCFAs, inhibited cell proliferation and induced apoptosis." (PMID 33113952, 2020).
diabetes (27 papers, 2014 to 2025). "One such SCFA produced by glucose fermentation, butyric acid, activated free fatty acid receptor 2 (Ffar2), efficiently increased insulin to ameliorate diabetes, and inhibited high fat diet (HFD)-induced abdominal fat in mice." (PMID 39253113, 2024). "Increasing studies has shown that free fatty acid receptors (FFARs), especially FFAR2, have excellent protective effects against cardiovascular diseases, including diabetes, myocardial ischemia reperfusion, hypertension, arrhythmias, and so on." (PMID 39228788, 2024). "Studies have shown that hub genes including LRRK2 and FFAR2 have been reported to be correlated with prognosis in a diabetes mellitus." (PMID 38137330, 2023). "FFAR2 agonists can be used as a new insulin sensitizer for type 2 diabetes mellitus, with therapeutic potential in this disease." (PMID 32411444, 2020). "FFAR2 mRNA and protein expression were similar in type 2 diabetes mellitus patients compared to CON." (PMID 30190473, 2018). "Given that ME1, FFAR3, and FFAR2 are all candidate targets for anti-diabetes drugs, further elucidation of the networks/pathways that involve these molecules may prove valuable." (PMID 37047583, 2023). "Furthermore, butylated high-amylose maize starch administration to FFAR2 KO-NOD mice show protection against diabetes due to an increase in the population of CD4+Foxp3+ Treg cells in the colon." (PMID 32521775, 2020). "Thus, it is worth investigating whether butyric acid controls the activity of Ffar2 or HDAC to regulate the insulin secretion in different types of diabetes." (PMID 32404878, 2020). "Our findings demonstrate higher normalized FFAR2 expression in MAFLD patients compared to controls, with similar observations in patients with type 2 diabetes mellitus (T2DM)." (PMID 38932276, 2024). "Among them, the free fatty acid receptor (FFAR) FFAR1 (GPR40), FFAR2 (GPR43), FFAR3 (GPR41), and FFAR4 (GPR120) may bridge the genetic and environmental aspects of diabetes (14, –, 18)." (PMID 37787527, 2023). "This increased signaling through GRP119, FFAR2/3 and their downstream effects through GLP-1 and SGLT1/GLUT2 mediated by sweet taste receptors represent a potential mechanism for improved glycemic control in diabetes following RYGB gastric bypass." (PMID 36034439, 2022). "The FFAR2 mRNA level was not correlated with type 2 diabetes mellitus (p=0.836), nor with the level of fasting blood sugar (p=0.339)." (PMID 32411444, 2020). "Logistic regression analysis showed that low expression of the FFAR2 gene in peripheral blood was a risk factor for AMI, independent of age, history of diabetes mellitus, fasting blood glucose level, and HDL-C level (p=0.025)." (PMID 32411444, 2020). "FFAR2 protein expression neither correlated with OGIS in type 2 diabetes mellitus patients nor in CON." (PMID 30190473, 2018). "To this end, we analyzed FFAR2 as well as FFAR4 and SCD1 mRNA and protein expression in SAT of 25 metabolically well-characterized patients with newly diagnosed type 2 diabetes mellitus and 25 age-matched, sex-matched, and BMI-matched glucose-tolerant humans (CON)." (PMID 30190473, 2018). "However, acetylated high-amylose maize starch administration to FFAR2WT-NOD mice shows protection against diabetes but such effect was no seen in FFAR2 KO-NOD mice." (PMID 32521775, 2020). "Logistic regression analysis suggested that the low expression of the FFAR2 gene in peripheral blood may be a risk factor for AMI independent of age, family history of diabetes, fasting blood glucose level, and HDL-C level (p=0.025)." (PMID 32411444, 2020). "Our findings suggest that SCD1 expression may be important in early development of type 2 diabetes mellitus, but is not as effective in modulating beta cell function as FFAR2." (PMID 30190473, 2018). "Thus, both FFAR2 and SCD1 may be potential treatment targets in diabetes prevention strategies." (PMID 30190473, 2018).
diabetes (continued). "In conclusion, patients with recent onset type 2 diabetes mellitus have lower SCD1, but not FFAR2 or 4 expression in SAT compared to CON." (PMID 30190473, 2018).
Hypertension (23 papers, 2020 to 2025). The presence of chronic increased pressure in the systemic arterial system. "In mice, FFAR2 and FFAR3 protect against hypertension through immune-mediated mechanisms." (PMID 41291732, 2025).